EGFR (epidermal growth factor receptor)
Diseases named in the same sentence as EGFR in open-access papers (continued):
Sharing a sentence is not in itself a finding about the gene and the disease.
cancer (continued). "Here, we show marked synergy between vertical inhibition of EGFR and SOS1 in EGFR mutated cancer cells, but only under 3D culture conditions." (PMID 32897190, 2020). "Overexpression of the epidermal growth factor receptor (EGFR) associates with a range of cancers while downregulation of EGFR signalling can inhibit cancer growth." (PMID 33287803, 2020). "CTV-1 and HCC-827 are both mono-driver cancer cells driven by mutated Lck kinase and EGFR, respectively." (PMID 32349331, 2020). "The detection of EGFR mutations in circulating cell-free DNA can enable personalized therapy for cancer." (PMID 32093010, 2020). "While these drugs are often initially effective against cancers with mutated EGFR, some patients acquire resistance due to the development of secondary, often activating mutations in exon 20 (e.g., T790M)." (PMID 32784650, 2020). "Anti-epidermal growth factor receptor (EGFR) drugs used during cancer treatment cause TRPM6 upregulation and consequent hypomagnesemia in renal tubular epithelial NRK-52E cells." (PMID 33291725, 2020). "Our study provides a framework for the systematic, preclinical assessment of therapeutic combinations designed to treat EGFR-mutated cancer cells." (PMID 32897190, 2020). "The present study showed the comprehensive analysis of disease characteristics and treatment patterns in uncommon EGFR mutation-positive NSCLC at a major cancer center." (PMID 33036377, 2020). "In this work, we approached three human oncogenes, BRAF, KRAS, and EGFR, and studied the mutation-specific probes as duplexes with a fragment of cancer RNA." (PMID 36703315, 2020). "Activating mutations in the epidermal growth factor receptor (EGFR) gene occur as early cancer-driving clonal event in a subset of NSCLC patients (approximately 15% of Caucasian patients) and predict sensitivity to EGFR tyrosine kinase inhibitors (TKIs)." (PMID 33520716, 2020). "Mutation, increased expression, and amplification of EGFR that deregulate the EGFR signaling are linked with the development of a variety of human cancers." (PMID 32559195, 2020). "The majority of NSCLC cancer harboring actionable EGFR mutations occurs in adenocarcinoma histology." (PMID 33291316, 2020). "Epidermal growth factor receptor tyrosine kinase inhibitors (EGFr TKIs) are first‐line therapies for various cancers, and cause dose‐limiting severe diarrhea in many patients." (PMID 32652816, 2020). "The upregulation of EGFR has been confirmed in betel-nut-associated cancer of the oral cavity associated with poor prognosis." (PMID 32974098, 2020). "Aberrant growth factor receptor signaling by members of the EGFR family is linked to cancer and all four members (EGFR, HER2, HER3 and HER4) were shown to contribute to cancer cell growth, migration and metastasis formation." (PMID 33260837, 2020). "The combination of cetuximab and AurkA/B inhibitors can improve treatment efficiency in any EGFR polymorphism-based therapeutic resistance in cancer cells." (PMID 35047986, 2020). "Studies have documented that the overexpression of Epidermal Growth Factor Receptor (EGFR) is associated with high cancer cell proliferation and high risk of recurrence in patients receiving treatments." (PMID 32080195, 2020). "Mitogenic and prosurvival signaling pathways downstream of EGF binding to the EGFR are key to mediating cell proliferation, and activating mutations in EGFR are commonly found in many types of cancers." (PMID 32759334, 2020). "Since the EGFR signaling is associated with the apoptosis, proliferation and invasion of cancer cells, the EGFR was investigated as a therapeutic target in previous studies." (PMID 33353229, 2020).
cancer (continued). "This single locus accounts for almost 90% of the estimated genomic instability in the exon 19 canonical deletion, the most common cancer-linked mutation in the EGFR gene." (PMID 31940362, 2020). "Threonine 790 is the gatekeeper for EGFR because it is located at the entrance to the hydrophobic ATP-binding pocket; this mutation promotes cancer cell proliferation via increasing the catalytic activity of EGFR." (PMID 32549388, 2020). "Synthetic multivalent antibodies retargeted (SMART) EV bear monoclonal antibodies against CD3 and cancer cell-associated epidermal growth factor receptor (EGFR)." (PMID 33117718, 2020). "CUB-domain containing protein 1 (CDCP1) is a cancer associated cell surface protein that amplifies pro-tumorigenic signalling by other receptors including EGFR and HER2." (PMID 32104500, 2020). "K-ras codon 12 mutations are commonly occurring mutations in different types of cancers and leads to resistance against anti-EGFR therapeutics." (PMID 32042390, 2020). "The potential anti-cancer properties of krill oil are likely to be associated with the downregulation of EGFR, pEGFR and their downstream pERK/ERK1/2 and pAKT/AKT signalling pathways along with the downregulation of PD-L1." (PMID 33287803, 2020). "Epidermal growth factor receptor (EGFR) is upregulated in many cancer types and is associated with cancer progression and poor prognosis." (PMID 33050158, 2020). "Yu et al68 designed a “modified PNA‐PCR method” to screen KRAS mutation in cancer patients, this mutation shows resistance to epidermal growth factor receptor (EGFR) target therapy." (PMID 32838227, 2020). "By contrast, Epidermal growth factor receptor (EGFR) alterations have been implicated in the malignant progression of this type of cancer." (PMID 31947645, 2020). "EGFR-targeting therapy have been approved for the treatment of cancer with EGFR-overexpression/mutation." (PMID 32745124, 2020). "In conclusion, inhibition of metastatic activity by PLAG is mainly dependent on interference with the PAR2/EGFR/EMT signal cascade caused by prompt PAR2 degradation in cancer cells in the presence of neutrophils." (PMID 32121107, 2020). "The drug targets cancer cells that contain the T790M mutation in the gene coding for EGFR but spares cancer cells with wildtype EGFR." (PMID 33013366, 2020). "We have already demonstrated that TPP11 renders cancer cells susceptible to anti-EGFR therapy in PDAC xenograft models." (PMID 32560565, 2020). "Previous studies show that VEGF and EGFR expression are all associated with estrogen receptor status in patients with cancer." (PMID 32256653, 2020). "We selected 59 cancer tissues from the tissue microarray and found that the high EGFR staining group is largely associated with the low staining group of LXR-α (p < 0.01, r = −0.424), and vice versa." (PMID 33224867, 2020). "Those inhibitors, including dacomitinib, tomivosertib, BAY1143269, and ETC-1907206, have been developed for various types of EGFR mutation-positive cancers mainly including NSCLCs and various types of clinical trials are currently undergoing." (PMID 32983988, 2020). "In the current study, the EGFR mutation detection rate in plasma was considerably low in early-stage cancer (stage I/II), similar to reports by other studies." (PMID 32224854, 2020). "The nuclear increase of EGFR has been associated with cancer malignancy, poor patient survival, and drug resistance." (PMID 32321917, 2020). "Case reports have described germline mutations in the kinase domain of the EGFR, such as R776G, R776H, T790M, V843I and P848L, which confer a greater risk of cancer development." (PMID 32104210, 2020). "In conclusion, our study showed that a lower lobe cancer is associated with a higher all-cause mortality risk in patients with NSCLC, which is partly mediated by a lower proportion of EGFR mutations in lower lobe cancers." (PMID 32913267, 2020).
cancer (continued). "When existing separately, activating EGFR mutations are well defined predictive effects of EGFR-TKIs in NSCLC cancer patients, and while coexisting with KRAS mutations and ALK or ROS1 gene rearrangements, the EGFR-TKIs are predicted to be resistant." (PMID 32770988, 2020). "One of the most common pathways often implicated in cancer is the EGFR/RAS/PI3K/PTEN/AKT/GSK-3/mTORC1 pathway." (PMID 32365809, 2020). "In other cancer types such as lung, ctDNA testing for EGFR mutation status has been approved by the Food and Drug Administration (FDA) to guide selection of therapy." (PMID 33033274, 2020). "Thirty-one percent of patients with EGFR mutations were diagnosed with EI-H-type cancer, and the remaining patients were diagnosed with EI-L-type cancer." (PMID 32277151, 2020). "Upstream regulators and causal networks predicted suggested a close link to EGFR mutation-positive cancers, mainly NSCLC." (PMID 32983988, 2020). "For the detection of EGFR mutation, the target panel, i.e., AmpliSeq for Illumina Cancer Hotspot Panel v2 was used." (PMID 32033355, 2020). "Uncontrolled EGFR signaling promotes tumorigenesis and is a hallmark of different types of cancers, including glioblastoma, lung, colorectal, pancreatic, and head and neck carcinomas." (PMID 33202887, 2020). "In this study, we analyzed a large number of 10,000 patients with advanced cancers for oncogenic mutations in EGFR, ERBB2, BRAF, and MAP2K1, especially for those located within the kinase domain β3‐αC loop." (PMID 32757330, 2020). "Previous research has shown that aberrant activation of EGFR is closely associated with cancer cell properties such as growth, malignancy, and metastasis." (PMID 33158043, 2020). "ECM molecules like Fibulin-3, Tenascin-C and Emilin-2 have been known to associate with growth factor receptors like EGFR to regulate its activation and function during cancer progression." (PMID 32719793, 2020). "Nevertheless, primary or acquired resistance to EGFR inhibitors is the most common cause of cancer relapse and progression." (PMID 32517369, 2020). "Unfortunately, the presence of innate or the onset of acquired resistance to EGFR inhibitors remains the most common cause for cancer relapse and mortality, highlighting the importance to investigate the complex network of cancer resistance mechanisms." (PMID 32517369, 2020). "EGFR mutation is a frequent cancer-driving event in NSCLC, occurring in about 40–50% of cases in Asia and 20–30% in the United States30." (PMID 32792499, 2020). "Afatinib has been shown to be more effective in in vitro studies than osimertinib when used in cancer cell lines containing some specific EGFR mutations." (PMID 32495514, 2020). "EGFR over-expression in cancer cells is closely associated with poor clinical prognosis, reduced survival rate and more aggressive phenotype." (PMID 33023595, 2020). "The epidermal growth factor receptor (EGFR) family plays an important role in growth and development, and its alteration is associated with a variety of conditions, including cancer." (PMID 32020871, 2020). "EGFR was found to be overexpressed in very high amounts in various cancer types and is associated with a strongly enhanced proliferation rate of cancer cells." (PMID 32733853, 2020). "Mice immunized with WHTEILKSYPHE-KLH or LPAFFVTNQTQD-KLH developed high-titer Abs that recognized both EGFR and its variant EGFRvIII overexpressed on cancer cells." (PMID 32075083, 2020). "Here, we describe the physical and functional interaction between c-Src and EGFR—both ubiquitously expressed and often over-expressed and/or mutated (i.e., EGFR) in cancer cells—and their involvement in cancer as well as in drug resistance." (PMID 32517369, 2020).
cancer (continued). "EGFR signal transduction regulates many cellular activities including migration and invasion and is also implicated in certain cancers." (PMID 32823904, 2020). "MDM2/4 as well as EGFR amplifications are supposed to be associated with hyperprogression on ICI in diverse cancers." (PMID 32110946, 2020). "Afatinib is thought to be effective for treating resistant cancers containing minor and compound EGFR mutations and HER2 amplification after osimertinib treatment." (PMID 32495514, 2020). "The discordance between the diagnostic biopsy and resection specimens for both HER2 and EGFR status, demonstrates potential heterogeneity of expression in these cancers or indeed a neoadjuvant treatment effect." (PMID 31765988, 2020). "Many studies reported that the mutations in some cancer-related genes such as EGFR contribute to the tumorigenesis and progression of LUAD, as well as drug resistance." (PMID 32117639, 2020). "The gene interaction map of the SNPs that were found to interact with the Group 1 features reveals three individual cancer-related networks, among which the EGFR-BLK-ATR- and WWOX-linked networks are noticeable." (PMID 32632202, 2020). "EV membrane-associated proteins, including NY-ESO-1, EGFR and EpCAM, have been found to have prognostic value in cancer patients." (PMID 33260345, 2020). "Activating epidermal growth factor receptor mutations were detected in four patients among 111 tested cancers." (PMID 33218332, 2020). "Abnormal activation of EGFR is known to occur mainly via overexpression, mutation, or autocrine stimulation of EGFR in cancers." (PMID 33246423, 2020). "In normal cells, EGFR is involved in growth factor signaling, while cancer-associated oncogenic changes (mutations, overexpression, variant expression) often confer ligand independent oncogenic activity." (PMID 32650387, 2020). "Histological grade and Ki67 have been shown to be significantly associated with positivity to EGFR activating mutations or gene amplification which are common oncogenic events in some cancers." (PMID 32298357, 2020). "The purpose of this study was to investigate potential associations among TIMP-3 genetic polymorphisms, EGFR statuses, and cancer clinicopathologic development in patients with LADC." (PMID 33126605, 2020). "It is reported that cancer cells with the EGFR gene mutation (in particular, exon19del E746-A750 and L858R) respond to Gefitinib." (PMID 32605095, 2020). "The compound 12-epi-scalaradial found in G. cincta and G. hikuerensis is the most active, inhibiting the epidermal growth factor receptor (EGFR) implicated in many cancers, and also inhibiting the human recombinant PLA2 at 0.02 μM." (PMID 33371188, 2020). "Another possibility is that it activates the Ras-MAPK pathway, which is also downstream of EGFR and is also implicated in cancer development." (PMID 32398315, 2020). "EGFR is frequently mutated or overexpressed in cancer cells and abnormal activation of Ras in the EGFR pathway results in pro-tumorigenic proliferation and migration." (PMID 33138914, 2020). "To date, several evidence have suggested that EGFR-mutated cancer cells represent a crucial hallmark of immunosuppression, actively establishing an immunosuppressive milieu and negatively influencing the quality of T-cell immune response." (PMID 32760402, 2020). "A higher than expected number of KRAS and EGFR mutations were observed among adenocarcinoma cases, with fewer than expected among squamous cell and other cancer types (p-value of <0.0001)." (PMID 32756609, 2020). "Cancer cells harboring EGFR-activating mutations have been shown to be highly sensitive to the EGFR tyrosine kinase inhibitor (TKI) gefitinib, which was first approved in Japan in 2002." (PMID 32130260, 2020). "Known resistance factors to EGFR-targeted therapies in other cancer types include mutations and overexpression of the receptor tyrosine kinases AXL or MET." (PMID 32119655, 2020).
cancer (continued). "It is well known that, in cancer, somatic mutations in EGFR lead to its constant activation with the result of an uncontrolled cell division." (PMID 32365798, 2020). "Previously,a study revealed that both EGFR expression and gene copy number variations are associated with poor prognosis of cancers." (PMID 32535812, 2020). "Epidermal growth factor receptor (EGFR) is upregulated in several cancers, and has emerged as a target for diagnostic imaging and therapy." (PMID 32325827, 2020). "Stage four NSCLC harboring EGFR mutation was the first cancer entity to be treated with a targeted therapy in first line treatment." (PMID 32095117, 2020). "Targeting EGFR by EGFR- tyrosine kinase inhibitors (TKIs) has opened a new avenue in cancer therapy, as EGFR mutation frequently occurs in a large number of cancers including NSCLC." (PMID 33015045, 2020). "Despite the relevant antitumor efficacy of immunotherapy in advanced non-small cell lung cancer (NSCLC), the results in patients whose cancer harbors activating epidermal growth factor receptor (EGFR) mutations are disappointing." (PMID 32760402, 2020). "Mutations in this EGFR domain have been identified in human cancer and result in activation of EGFR signaling." (PMID 32813746, 2020). "Blood samples were obtained from cancer patients with defined driver gene hotspot mutations, including EGFR-T790M (n = 32), EGFR-L858R (n = 28), BRAF-V600E (n = 13), PI3KCA-E545K (n = 13), KRAS-G12C (n = 13), and KRAS-G12V (n = 6)." (PMID 32180799, 2020). "PDPN-positive cancer-associated fibroblasts (CAFs) contributed to an essential role in primary resistance to epidermal growth factor receptor tyrosine kinase inhibitors (EGFR-TKI)." (PMID 33123464, 2020). "Given that EGFR is expressed on normal cells, it would be worthwhile to target variants of EGFR that are only expressed on cancer cells." (PMID 32957689, 2020). "Unexpectedly, genetic EGFR mutations (T790M, L858R) were detected in at least 12% of carcinoma cells." (PMID 32033355, 2020). "In contrast, activating RAS (KRAS/NRAS) mutations have been identified as biomarkers for cancer cell resistance to monoclonal antibodies directed to epidermal growth factor receptor (EGFR)." (PMID 30565083, 2019). "For example, MET and EGFR are well-known to cause mutual cross-resistance to targeted therapy in different cancer types." (PMID 30881919, 2019). "Gefitinib is a selective inhibitor of EGFR and reported to be effective in cancers with mutated and overactive EGFR22,23." (PMID 31316108, 2019). "Targeted therapy with epidermal growth factor receptor-tyrosine kinase inhibitor (EGFR-TKI) has been approved as the first-line treatment of EGFR mutation-positive cancer." (PMID 31462678, 2019). "Overexpression of EGFR is a significant finding in cancer, particularly in HNSCC, where it is positively associated with a poor prognosis of patients." (PMID 30777099, 2019). "There are two types of pathological alterations of EGFR in cancers, one is kinase-activating mutation in EGFR and the other is over-expression of the EGFR protein." (PMID 31508364, 2019). "EGF functions as a ligand to activate the EGF receptor (EGFR) and dysregulation of EGF and/or EGFR is known to cause various types of human cancers." (PMID 31167465, 2019). "The EGFR gene is located at the chromosomal region 7p12 and encodes a 70 kDa transmembrane tyrosine kinase receptor that contributes to cancer progression by mediating cellular proliferation, migration, adhesion, and metastasis." (PMID 30530570, 2019). "Intense research efforts regarding cancer genomes have identified several oncogenic pathways important in human cancers, and have led to improved therapeutic outcomes for tumors with EGFR, ALK, and BRAF mutations." (PMID 31848373, 2019).